MIR663A (microRNA 663a)
Synonyms: hsa-mir-663; miR-663a; MIR663; MIRN663; hsa-mir-663a
Gene: MicroRNA gene on chromosome 20 (26,208,186 to 26,208,278, reverse strand). Ensembl gene ENSG00000284419.
Gene Ontology:
Biological process: miRNA-mediated post-transcriptional gene silencing
Diseases named in the same sentence as MIR663A in open-access papers:
MIR663A is named in the same sentence as 5 diseases in open-access papers, as found by Europe PMC text mining. Sharing a sentence is not in itself a finding about the gene and the disease. The quoted sentences say what the papers report.
cancer (1 paper, 2024). A tumor composed of atypical neoplastic, often pleomorphic cells that invade other tissues. "Functionally, both MIR483 and MIR663A have been shown to suppress apoptosis in cancer cells, and this might also be related to the phenotype observed in our study." (PMID 38886809, 2024).
tumor (1 paper, 2023).
MIR663A also shares sentences with these, for which no sentence is quoted: breast carcinoma (1 paper); pancreatic adenocarcinoma (1); pancreatic cancer (1).